FGFR3 (fibroblast growth factor receptor 3)
Diseases named in the same sentence as FGFR3 in open-access papers (continued):
Sharing a sentence is not in itself a finding about the gene and the disease.
multiple myeloma (102 papers, 2002 to 2025). "FGFR3 aberrations are implicated in several cancers, including bladder, urothelial, multiple myeloma, endometrial, pancreatic exocrine, and renal cell carcinoma." (PMID 40943615, 2025). "Dovitinib targets FGFR1/2/3 and is under clinical trial investigation as an anti-tumor drug, with FGFR1 chromosomal translocation associated with 8p11 myeloproliferative syndrome, and FGFR3 is implicated in multiple myeloma and peripheral T-cell lymphoma." (PMID 38002949, 2023). "This study aimed to investigate the influence of FGFR3 gene mutations on the clinical characteristics and prognosis of patients with newly diagnosed multiple myeloma (NDMM)." (PMID 38503521, 2023). "Generated gatekeeper FGFR3-V555M mutation in KMS-11 myeloma cells with acquired resistance to AZ12908010 caused cross-resistance to two other FGFR inhibitors, AZD4547 and PD173074." (PMID 34830951, 2021). "Although FGFR3 mutations have also been found in multiple myeloma and carcinoma of the cervix, their frequency in these malignancies is much lower than in urothelial cancers." (PMID 33912469, 2021). "The FGFR3 V555M mutation was identified in KMS-11 multiple myeloma cells (FGFR3 Y373C) made resistant to the FGFR inhibitor AZ12908010." (PMID 35582593, 2019). "FGFR3 mutations have been described in spermatocytic seminoma, multiple myeloma and cervical cancer." (PMID 31528172, 2019). "Oncogenic fusions of FGFR1 with various fusion partners were described in myeloid proliferative neoplasms, and overexpression and mutations of FGFR3 are common in multiple myeloma." (PMID 30755670, 2019). "FGFR3 mutations have also been identified in many other cancer types, including 3% of squamous cell lung carcinoma, cervical cancers, multiple myeloma, prostate cancer and spermatocytic seminomas." (PMID 28030802, 2017). "In contrast, FGFR3 protein expression was significantly associated with shorter survival in multiple myeloma." (PMID 28056982, 2017). "Overexpression, activating mutations and activating gene fusions in FGFR3 have also been identified in multiple myeloma, glioblastoma multiforme, bladder, cervical, gastric, colorectal, head and neck squamous, and germ cell-derived cancers." (PMID 27056048, 2016). "FGFR-3 mediated neoplasm has been reported in bladder cancer, multiple myeloma, cervical and prostate cancer, and FGFR-4 mutation has been reported in cases of bladder rhabdomyosarcoma and breast cancer." (PMID 27051190, 2016). "In contrast, the FGFR1-equivalent substitution in FGFR3 (V555M) is highly likely to occur and was previously identified in the context of a cancer cell line (multiple myeloma KMS-11) dependent on an FGFR3 Y373C driver mutation." (PMID 26097890, 2015). "Dysregulation of FGFR3 signaling has been implicated in several cancer types, most notably urothelial cell carcinoma (UC) and multiple myeloma (MM)." (PMID 24466111, 2014). "For example in pre-clinical studies of multiple myeloma, tumor cells are resistant to inhibition of the Fibroblast Growth Factor Receptor 3 (FGFR3) in the presence of a RAS mutation." (PMID 21072204, 2010). "Activating mutations in FGFR3 have been observed both in the ligand-binding and kinase domains in multiple myelomas, as well as in cancers of the bladder and cervix." (PMID 20234367, 2010). "In addition to dysplasias, abnormal FGFR3 activation is frequently found in various types of somatic cancers, and it is associated with poor prognosis or higher risk of recurrence in multiple myeloma (MM), bladder carcinoma, and cervical cancer." (PMID 37824212, 2023). "Furthermore, FGFR3 mutations are found in uterine cervical cancer (16.3%), including invasive cervical cancer (5%), myeloma (2.16%), and spermatocytic seminoma (6.66%)." (PMID 35494629, 2022).
multiple myeloma (continued). "Additionally, in a myeloma cell line resistant to AZ12908010 with a gatekeeper mutation in the FGFR3 gene, a secondary gatekeeper mutation was identified, resulting in the development of cross-resistance to two other FGFR inhibitors, AZD4547 and PD173074." (PMID 34830951, 2021). "Some cases of multiple myeloma are seen to express both mutation and over-expression of FGFR3." (PMID 31528172, 2019). "For FGFR3, mutation of the IIIc variant causes tumour growth in multiple myeloma cells." (PMID 20234367, 2010). "Interestingly, the relative frequency of different FGFR3 mutations is dependent on the tumour type, with multiple myeloma mostly showing changes in the tyrosine-kinase domain, and bladder and cervical tumours mainly exhibiting mutations of the extracellular region." (PMID 22899908, 2012). "Further analysis showed that Pa reduced excessive FGFR3 signaling by decreasing its half-life in FGFR3-overactivated multiple myeloma cells and chondrocytes." (PMID 37824212, 2023). "In the FGFR3‐mutant myeloma cell line KMS‐11, this produced a stable resistant derivative with a mutation (V555M) in the gatekeeper residue of FGFR3 that is predicted to limit drug access to the ATP binding site." (PMID 36385700, 2023). "Overexpression of FGFR3 decreases apoptosis in multiple myeloma cells, with concomitant increase in STAT3 phosphorylation and Bcl-xL expression." (PMID 34830951, 2021). "MGFR1877S is an mAb targeting FGFR3 by hampering its dimerization, which is well tolerated with low toxicities in patients with multiple myeloma and solid tumors in phase I clinical trials." (PMID 32879300, 2020). "MFGR1877S, an anti-FGFR3 antibody, showed very promising results in preclinical studies, but tested in phase I clinical study for urothelial cancers and multiple myeloma yielded equivocal results." (PMID 30134556, 2018). "Recently, a study, concerning the pathogenesis of multiple myeloma, indicated that FGFR3 was regarded as a targeted gene of miR-24-3p." (PMID 29850625, 2018). "Studies about multiple myeloma illustrated that regarded as an oncogene, FGFR3 promoted occurrence and development of tumors and was escalated in several other types of tumor, indicating its negative effects in cancer pathogenesis." (PMID 29850625, 2018). "One research recently further demonstrated that FGFR3 was targeted by miR-24-3p in multiple myeloma." (PMID 29850625, 2018). "FGFR3 and eIF4E were previously reported to frequently overexpress in lung cancer, myeloma, and ovarian cancers, thus playing an important role in tumor occurrence and development." (PMID 29545752, 2018). "Neutralizing antibody-like PRO-001 are other therapeutic molecules which selectively inhibits the proliferation of FGFR3-transformed cells and induces apoptosis of FGFR3-expressing human myeloma cells." (PMID 27051190, 2016). "In MM RSK2 signaling has been reported to be associated with FGFR3 (t;4,14) activation and a number of RSK2 inhibitors have been shown to have anti-myeloma activity." (PMID 27655636, 2016). "We further demonstrate a role for TAK1 as a positive regulator of NFκB activity downstream of FGFR3 in both multiple myeloma and urothelial cell carcinoma, two cancers with demonstrated FGFR3 involvement, with modulatory effects on cell adhesion." (PMID 24466111, 2014). "NDGA has been reported to inhibit an activated FGFR3 mutant and block downstream signaling in multiple myeloma cells." (PMID 24980830, 2014). "Conversely, multiple myelomas can harbor a t(4:14) intergenic translocation bringing FGFR3 gene under the control of the strong immunoglobulin heavy chain promoter, participating in tumor progression." (PMID 23902722, 2013). "Other studies implicate RSK2 in transmitting the prosurvival and proliferative signals from oncogenic mutant receptor tyrosine kinase FGFR3 in multiple myeloma, resulting in cell transformation." (PMID 19036157, 2008).
multiple myeloma (continued). "A mutation in the activation loop of the FGFR3 kinase domain (Lysine to Glutamic acid change), leading to constitutive activation of FGFR3, has been identified in patients with multiple myeloma, bladder and cervical carcinomas." (PMID 12402142, 2002). "Additionally, it has been described that NDGA inhibits several RTKs, such as IFG-1R in breast and prostate cancer cells and FGFR3 in multiple myeloma cells." (PMID 39519155, 2024). "Furthermore, the mAb MGFR1877S inhibiting FGFR3 dimerization has been shown to have positive results in the treatment of multiple myeloma and solid tumors." (PMID 34830951, 2021). "Because the same genetic lesions leading to FGFR3-related skeletal disorders cause FGFR3-driven cancers (e.g., bladder tumors and multiple myeloma), FGFR inhibitors that have been investigated for FGFR3-driven cancers can be repurposed for the treatment of ACH." (PMID 33262386, 2020). "CHIR-258, a potent inhibitor of Flt3 (fms-like tyrosine kinase receptor-3), c-Kit tyrosine kinase, and fibroblast growth factor receptor 3 (FGFR3), prevented cell growth of FGFR3-positive human multiple myeloma cell lines and augmented their sensitivity to GC-induced apoptosis." (PMID 23431463, 2013). "FGFR3 mutations are frequent in benign skin tumours and have been reported at low frequency in cervical carcinoma and multiple myeloma, but are absent in other solid cancers, suggesting a tissue-specific role." (PMID 22899908, 2012). "In a recent report, AZD1480 blocked both JAK/STAT3 and FGFR3 signaling in myeloma cells." (PMID 23056499, 2012). "Activation of the fibroblast growth factor 3 (FGFR3) expressed by myeloma cells and its ligand FGF present in the mouse could sustain in vivo angiogenesis such as in the bone marrow milieu." (PMID 20459741, 2010). "Chell and his colleagues sequenced a KMS-11 myeloma cell line resistant to AZ12908010, and found the FGFR3 gatekeeper mutation V555M, which conferred cross-resistance to AZD4547 and PD173074 by an increase in FGFR3 phosphorylation and an improvement of downstream signaling transduction." (PMID 33568192, 2021). "Mutation of at least one out of five genes (cyclin D1, C-MAF, FGFR3/MMSET, cyclin D3 and MAFB) seems to be a consistent finding in plasma cell myeloma which requires about three such rate limiting steps on average to manifest clinically." (PMID 40720480, 2025). "Translocations bring different oncogenes (such as Cyclin D1 (CCND1), CCND3, fibroblast growth factor receptor 3 (FGFR3), multiple myeloma SET-domain (MMSET/WHSC1), MAF or MAFB) under the control of the IgH enhancer." (PMID 33916289, 2021). "Targeted inhibition of RSK2 effectively induced apoptosis in FGFR3-expressing myeloma cells, suggesting that RSK2 is a critical signaling effector in FGFR3-mediated hematopoietic transformation." (PMID 34202904, 2021). "Inhibiting the activity of FGFR3 by PD173074 and/or SU5402, taken as an example, resulted in cell death of multiple myeloma." (PMID 29850625, 2018). "This translocation results in increased expression of fibroblast growth factor receptor 3 (FGFR3) and multiple myeloma SET (MMSET) domain." (PMID 29250532, 2017). "And also, they mentioned that there was no relevance between high-grade multiple myeloma and the high expression level of FGFR3." (PMID 41228379, 2025). "The data also rules out abnormalities involving MAF, MAFB, MYC or NSD2/FGFR3, which are chromosomal translocations clinically relevant for multiple myeloma diagnosis." (PMID 40027317, 2024).
multiple myeloma (continued). "Multiple myeloma is an incurable plasma cell malignancy, which is characterized by recurrent chromosomal aberrations that drive the expression of established oncogenes such as MYC, Cyclin D1, FGFR3/MMSET and MAF/MAFB." (PMID 33494394, 2021). "Studies of the novel selective FGFR inhibitors erdafitinib and AZD4547 look to target patients with alterations in the FGFR3 pathway specifically, though there are currently no published results of these agents in multiple myeloma patients." (PMID 35127532, 2021). "MIP-1α (CCL3) is a downstream target of FGFR3 and RAS-MAPK signaling in multiple myeloma." (PMID 34229750, 2021). "Next, we determined the presence of neutral and acid sphingomyelinase mRNA as well as total secreted and cellular SMase in human multiple myeloma cell lines (HMCL) representing different genetic subtypes of MM, including JJN3 (c-Maf), LP1 (MMSET/FGFR3), OPM2 (MMSET/FGFR3), and U266 (CCND1)." (PMID 31756922, 2019). "Other examples of translocation between IGH and other oncogenes are BCL2 in FL, BCL6 in diffuse large B cell lymphoma (DLBCL) and CCND1 (Cyclin D1), CCND3 (Cyclin D3), FGFR3/MMSET (Fibroblast growth factor receptor 3/multiple myeloma SET domain), and MAF (c-maf) in multiple myeloma (MM)." (PMID 28867784, 2017). "Furthermore, CK induced apoptosis and inhibits fibroblast growth factor receptor 3 (FGFR3) expression and signaling in myeloma cell line KMS-11, suggesting candidacy for the chemoprevention and the treatment of myeloma." (PMID 27446225, 2016). "However, such a huge gene amplification like IGH up to 6–8 copies is uncommon in patient-derived primary myeloma cells, and we were able to diagnose IGH/FGFR3 by having an appropriate threshold even in cells with a high number of IGH amplification like KMS-21BM cells." (PMID 36882509, 2023). "However, the Phase I study of the FGFR3-targeted ADC LY3076226, which showed an acceptable safety profile, did not enroll any myeloma patients." (PMID 37111346, 2023). "Although the subprotocol of the phase 2 MATCH basket study looked to treat only FGFR3-amplified tumors with AZD4547, no multiple myeloma patients were ultimately enrolled and the subprotocol failed to meet its goal of a 16% response rate among other cancers treated." (PMID 35127532, 2021).
breast carcinoma (80 papers, 2005 to 2025). "The basal subtype, with high expression of basal KRTs, has a worse prognosis and a greater similarity to basal-like subtypes in breast cancer, while the luminal subtype has a better prognosis and is associated with FGFR3 mutations." (PMID 39594166, 2024). "The FGFR3 gene (4p16.3) is mutated in a very low percentage of breast cancer patients, particularly in the extracellular and the transmembrane protein domains, and rarely within the kinase domain." (PMID 37296801, 2023). "Other studies have reported a correlation between MATH and survival in various cancer types, including breast cancer, lung adenocarcinoma, FGFR3-mutated muscle-invasive bladder cancer, melanoma, and uterine corpus endometrial carcinoma." (PMID 35565368, 2022). "In a study of 182 ER+ breast cancer patients, FGFR3 was mutated in 3 out of 126 (2.4%) primary samples and 1 out of 57 (1.8%) metastatic samples." (PMID 31987043, 2020). "FGFR3 has also been linked to an influence on endocrine resistance and the risk of breast cancer (e.g., via SNPs), but the amplification rate has been reported to be less than 1%." (PMID 32852708, 2020). "The TCGA and the Metabric datasets were analyzed using cBioportal to determine the frequency of FGFR3 alterations in terms of overexpression, mutation, amplification and deletion in different breast cancer subtypes." (PMID 31987043, 2020). "Conversely, there are studies reporting an association between the overexpression of the FGFR3 protein and poor survival in breast cancer." (PMID 27154171, 2016). "High levels of FGFR3 protein expression as well as FGFR4 mRNA expression were associated with poor prognosis of ER+ breast cancer patients receiving TAM treatment." (PMID 27533459, 2016). "The FGFR3 gene is associated with cancers such as BC, multiple myeloma, and breast cancer." (PMID 39219882, 2024). "Overexpression of FGFR3 was also linked with tamoxifen resistant breast cancer." (PMID 34830836, 2021). "In addition to FGFR1, fibroblast growth factor receptor 2 (FGFR2 gene, chromosome 10) and fibroblast growth factor receptor 3 (FGFR3 gene, chromosome 4) belong to the same family of receptor tyrosine kinases and are linked to breast cancer susceptibility." (PMID 32852708, 2020). "We speculate that the down-regulation of miR-99a is implicated in breast cancer carcinogenesis and progression through the regulation of FGFR3." (PMID 32038996, 2019). "FGFR3 expression is associated with poor prognosis in breast cancer." (PMID 31354524, 2019). "Association of FGFR2 and FGFR3 expression with ER+ breast cancer progression was observed." (PMID 29455658, 2018). "In this study, we genotyped two polymorphisms in the FGFR4 gene, rs1966265 and rs351855, and two polymorphisms in the FGFR3 gene, rs2234909 and rs3135848, and evaluated their association with breast cancer risk in women from Heilongjiang Province, northeast of China." (PMID 26431494, 2015). "In addition, recent studies also indicate that FGFR3 may function via a common molecular pathway causing breast cancer and may be a candidate therapeutic target in FGFR3-associated breast cancer." (PMID 31354524, 2019). "Twenty-three patients had an FGFR3 R248C mutation, corresponding to 11 UTUCs, nine UCBs, and three tumors with other primary sites (one squamous cell carcinoma of the lung, one lung metastasis from breast carcinoma, and one squamous cell carcinoma of the tongue)." (PMID 30854504, 2018). "These included several well-known cancer genes or their family members with previously less recognized role in breast cancer—FGFR3, FGFR4, NOTCH3, KMT2B, EP300, FLT4 and FAT1." (PMID 40858906, 2025). "Various inhibitors of FGFR3 are at various stages in phase I and phase II clinical trials for breast cancer." (PMID 39057065, 2024). "A rearrangement fusing exon 17 of the gene FGFR3 to exon 11 of TACC3 gene (1/140 – 0.7%) was detected with 184470 fusion mapped reads in patient operated for breast carcinoma brain metastasis." (PMID 39087020, 2024).